TMEM230 (transmembrane protein 230)
Diseases named in the same sentence as TMEM230 in open-access papers (continued):
Sharing a sentence is not in itself a finding about the gene and the disease.
tumor (7 papers, 2021 to 2025). "Patient-derived tumor gene expression analyses supported that TMEM230 has prognostic value as a tumor marker for aggressive HGG-ODG since a higher level of TMEM230 was associated with lower patient survival and worse prognosis." (PMID 38612777, 2024). "We therefore evaluated both the intracellular and extracellular roles of TMEM230 in promoting 3D sprouting and migration in U87 cells, features that may recapitulate tumor cell aggressive properties associated with GBM, such as invasion and vascular mimicry." (PMID 34867197, 2021). "Human TMEM230 emerges as a promising novel target for antiangiogenic and antitumor therapies due to its pleiotropic like regulatory role in tumor associated angiogenesis and invasive and vascular mimicry properties in U87 tumor cells." (PMID 34867197, 2021). "Our new study supported that the TMEM230 expressing U87 cells may secrete extracellular components and modulate their tumor microenvironment to promote tumor cell induced VM or endothelial associated angiogenesis." (PMID 34867197, 2021). "Inhibition of endogenous angiogenic promoting factors, such as TMEM230, are attractive targets for cancer therapy and tumor associated angiogenesis, as they may be less toxic and less likely to lead to drug resistance than exogenous inhibitors." (PMID 34867197, 2021). "Additionally, TMEM230 may protect cells in stressful environments or conditions, such as those associated with growth factor deficiency and/or hypoxic tumor cores." (PMID 34867197, 2021). "Like IFNs, RNASET2, syndecans, and TMEM230 appear to have both pro- and anti-cancer activities, depending on their levels of expression in different cells of the tumor mass." (PMID 40862725, 2025). "Tumor glial cells expressing TMEM230 displayed increased migration capacity and when confronted with ECs in their path in co-culture assays, infiltrated, enveloped or displaced ECs suggestive of the intussusceptive structural remodeling of blood vessels." (PMID 40141059, 2025). "Generation of 3D like vessel structures provided an additional role of TMEM230 for promoting perfusion of a tumor mass, necessary for continued aggressive tumor expansion and infiltration into tissue." (PMID 34867197, 2021). "Results support that U87 tumor cells expressing TMEM230 recapitulate blood vessel sprouting or the early steps in vessel formation without direct contact with HUVECs." (PMID 34867197, 2021). "In this study we demonstrated that TMEM230 represents a novel pleiotropic acting gene with both intracellular and extracellular tumor and vascularization in the form of vascular mimicry and angiogenic promoting capacities." (PMID 34867197, 2021). "TMEM230 therefore functions in two different cell types (glial and endothelial) to promote in tumor formation, tissue destruction and hypervascularization, and destabilization of existing normal blood vessels." (PMID 34867197, 2021). "Our study here supported that TMEM230 promoted angiogenesis by inducing sprouting and tubule-like structures in HUVECs and vessel like structures by tumor cells themselves through a process described as vascular mimicry." (PMID 34867197, 2021). "In this study, we demonstrated that downregulation of TMEM230 inhibited the adherence of U87 tumor cells both to the basement membrane like scaffold (Matrigel, cellulose or collagen) and to polystyrene surface of tissue culture plates." (PMID 34867197, 2021). "The cohort of 530 LGG patient samples was classified according to each tumor type and the expression level of TMEM230." (PMID 34867197, 2021). "Gene expression analysis of patients further suggested that TMEM230 played a role maintaining tumor cell adherence to the extracellular scaffold, necessary for tumor cell motility and invasion." (PMID 34867197, 2021). "This is in agreement with the identification that TMEM230 has both intracellular and extracellular activity in tumor development and tumor driven angiogenesis." (PMID 34867197, 2021).
tumor (continued). "Of interest and clinical importance is whether TMEM230 regulates tissue response to hypoxia and may be upregulated in the hypoxic tumor microenvironment." (PMID 38612777, 2024). "Elevated transmembrane protein TMEM230 in GBM can promote tumor cell migration, extracellular stent remodeling, and excessive blood vessels and abnormal formation of blood vessels, so TMEM230 has the potential be a therapeutic target for inhibition of GBM tumor cells and anti-angiogenesis." (PMID 38230206, 2024). "Our results support that the aggressive tumor behaviors of GBM and HGG may be associated with aberrantly high levels of TMEM230." (PMID 38612777, 2024). "If aberrant elevated levels of TMEM230 promote aggressive tumor development, TMEM230 may represent a promising target for cancer therapeutics." (PMID 38612777, 2024). "If this tumor progression model is valid, and aberrant elevated levels of TMEM230 promote aggressive tumor development by modulating the infiltrating properties of diverse types, TMEM230 may represent a significant target for cancer therapeutic research." (PMID 38612777, 2024). "This suggested that TMEM230 may protect tumor cells in conditions in which essential extracellular growth factors are reduced or absent as in the case of SR media conditions." (PMID 34867197, 2021). "The collective analyses provide insight into how TMEM230 may regulate cellular activities in tumor tissue remodeling and aberrant vascularization in tumor development and progression." (PMID 34867197, 2021). "Judicious and precise use of levels of TMEM230 for therapy may inhibit these tumor properties and also help to normalize blood vessel function in GBM." (PMID 34867197, 2021). "Additionally, when TMEM230 was down regulated in tumor cells, the tumor cells lost the ability for substratum adhesion and consequently, substrate dependent motility." (PMID 34867197, 2021). "Higher levels of TMEM230 promoted aggressive tumor behavior, remodeling and increased endothelial and tumor cell (vascular mimicry) based vascularization of 3D scaffolds through intracellular and extracellular activities of TMEM230." (PMID 34867197, 2021). "As our previous results showed that TMEM230 was expressed in diverse human tumor cell lines and patient tumor cells, this was suggestive that different tumors may utilize similar TMEM230 modulated genes and pathways for promoting tumor associated angiogenic switch." (PMID 34867197, 2021). "Our previous studies supported that in addition to IRF1, TMEM230, RNASET2, and SDC2 have tumor promoting and inhibiting functions." (PMID 40862725, 2025). "Therefore, the pathways enriched in GBM in which TMEM230 expression was elevated indicated that angiogenic switch associated with GBM was a process driven by the physical interactions of different cell types and scaffold or soluble factors present in the tumor environment." (PMID 34867197, 2021). "Moreover, this study combined with our previous research supports that precision regulation of TMEM230 epxression levels in patients may likely promote normalization of tumor formed abnormal blood vessels to allow for better delivery of antitumor therapeutic drugs." (PMID 34867197, 2021). "TMEM230 therefore is both a promising anticancer and antiangiogenic therapeutic target for inhibiting GBM tumor cells and tumor-driven angiogenesis." (PMID 34867197, 2021). "Targeting TMEM230 could inhibit GBM cell proliferation, tumour-driven angiogenesis, and antiangiogenic therapies." (PMID 38055673, 2023). "The collective results of our study support that TMEM230 promotes anchorage, motility, sprouting and branching like behavior in two diverse cell types found in GBM, tumor glial cells and resident tumor blood vessel cells, as demonstrated in U87 and HUVEC assays." (PMID 34867197, 2021). "To investigate whether TMEM230 has a role in the pathogenesis of GBM, we analyzed its prognostic value in patient tumor gene expression datasets and performed cell functional analysis." (PMID 34867197, 2021).
tumor (continued). "The U87 assays demonstrated TMEM230 expression was necessary for tumor cell motility and infiltration-like behavior and supported that aberrant elevated levels of TMEM230 expression promote intravasation and blood vessel branching in the GBM tumor." (PMID 34867197, 2021). "As the transition in gene and pathways profiles correlated with the levels of TMEM230 expression, our results support that TMEM230 is a novel clinical marker that may differentiate GBM from LGG tumor properties for application in patient diagnostics and prognosis." (PMID 34867197, 2021). "As TMEM230 sequence is conserved in human and zebrafish, we investigated whether TMEM230 is expressed in human tumors and may represent a promising novel drug target for antiangiogenic or antitumor therapy to restrict GBM tumor cell properties and tumor cell promoted angiogenesis." (PMID 34867197, 2021).
cancer (4 papers, 2021 to 2025). A tumor composed of atypical neoplastic, often pleomorphic cells that invade other tissues. "As TMEM230 regulates infiltration, vascularization, and tissue destruction capacities of diverse cell types in the brain, TMEM230 is a promising cancer target for heterogeneous HGG tumors." (PMID 38612777, 2024). "Our sequencing analysis presented in this study supports that aberrant modulation of TMEM230 expression may promote ER-induced stress, cell death, and mitochondrial dysfunction in both cancer and RA." (PMID 40141059, 2025). "Additionally, TMEM230 could recuperate normal function and 3D structural properties of aberrantly formed blood vessels such as induced in disease or cancer development." (PMID 34867197, 2021). "We also demonstrated that misexpression of the levels of TMEM230 and RNASET2 contributed to aggressive cancer features, including aberrant angiogenesis and destructive tissue remodeling, and a loss of normal cell-to-cell and cell-to-substratum attachments." (PMID 40141059, 2025). "The reason why misexpression of the levels of TMEM230 and RNASET2 occurs in certain cancers is unknown to us." (PMID 40141059, 2025).
movement disorder (1 paper, 2020). Neurological conditions resulting in abnormal voluntary or involuntary movement, which may impact the speed, fluency, quality and ease of movement. "Mutations in TMEM230 gene have been reported initially to play a pathogenic role in a rare autosomal dominant PD with typical movement disorders and Lewy body pathology." (PMID 32848711, 2020). "Mutations in transmembrane protein 230 (TMEM230) gene are suggested to be associated with the autosomal dominant Parkinson’s disease (PD) with typical movement disorders and Lewy body pathology." (PMID 32848711, 2020).
TMEM230 also shares sentences with these, for which no sentence is quoted: Parkinsonism (2 papers); age (1); Alzheimer disease (1); autoimmunity disorders (1); dependent (1); glial cell tumor (1); neurological disorders (1); oligoastrocytoma (1); osteoarthritis (1).